IL6 (interleukin 6)
Diseases named in the same sentence as IL6 in open-access papers (continued):
Sharing a sentence is not in itself a finding about the gene and the disease.
type 2 diabetes (continued). "A series of studies have demonstrated that a chronic and low-grade inflammation, characterized by the elevated pro-inflammatory cytokines such as TNF-α and IL-6, exists in obese and type 2 diabetic patients." (PMID 34621265, 2021). "who concluded that Escherichia-Shigella negatively correlated with weight gain and final weight of broilers; Escherichia-Shigella were positively correlated with IL-6 in rats with type 2 diabetes." (PMID 34721434, 2021). "Prevalence of P. copri in the feces and plasma interleukin-6 levels were increased in type 2 diabetes patients." (PMID 34419147, 2021). "Elevated levels of IL-6 and CRP are strongly associated with development of type 2 diabetes in healthy middle-aged women." (PMID 34867458, 2021). "Instead interleukin-6 was found to be a significant independent predictor of macrovascular events and mortality in this study including patients with type 2 diabetes." (PMID 34753497, 2021). "Myeloid cells from patients with T1D show increased secretion of IL-6 compared with control and type 2 diabetes patients." (PMID 34747368, 2021). "Elevated plasma concentration of IL-6 is a marker for development of type 2 diabetes and for myocardial infarction." (PMID 32524217, 2020). "ACEI were shown to inhibit LTA4 hydrolase (and consequently, LTB4 synthesis), to reduce monocyte chemoattractant protein-1 expression in macrophages and to decrease IL6 and tumor necrosis factor in normotensive type 2 diabetes individuals, among other effects." (PMID 32273829, 2020). "Our results indicate that type 2 diabetes patients with CRC had significantly higher IL-6 levels than controls, revealing associations between IL-6 levels and CRC." (PMID 33187505, 2020). "On the contrary, the GC and CC genotypes of the IL6 rs1800795 have been shown to be protective factors against type 2 diabetes." (PMID 32961860, 2020). "Various studies have examined the relationship between IL-6 and type 2 diabetes, finding IL-6 to be predictive of its onset." (PMID 33086688, 2020). "The skeletal muscle itself and muscle tissue infiltrating inflammatory cells produce IL-6, as observed in type 2 diabetes and inflammatory myopathies." (PMID 32077465, 2020). "A meta-analysis reported that increased levels of inflammatory markers such as IL-6 and CRP significantly increase the risk of incident type 2 diabetes." (PMID 31690939, 2020). "Studies have indicated that the level of proinflammatory cytokines, IL-1β and IL-6, descended significantly in inflammatory bowel disease 39, acute pancreatitis 40 and type 2 diabetes 17 after injection of HUMSCs." (PMID 32210708, 2020). "In vivo studies show that rhIL-6 enhances lipolysis and fat oxidation in healthy young and elderly humans and IL-6 autoantibodies appear to be involved in the pathogenesis of a subset of type 2 diabetes." (PMID 32393961, 2020). "Beyond conventional risk factors for type 2 diabetes, inflammatory markers such as fibrinogen, C-reactive protein (CRP), and interleukin-6 (IL-6) are also contributors to the development of type 2 diabetes." (PMID 31690939, 2020). "Other studies conducted in a senior population revealed a relationship between elevated levels of IL-6, CRP and diminished cognitive function, as well as an increased risk of type 2 diabetes." (PMID 31151190, 2019). "Higher concentrations of this cytokine have been found in visceral adipose tissue, while increased levels of IL-6 precedes episodes of acute cardiovascular events and the development of type 2 diabetes." (PMID 31500356, 2019). "Based on the findings of the meta-analysis in relation to the inflammatory parameters, low GI diets significantly decreased (p < 0.05) levels of interleukin-6 compared with the higher GI diets in patients with type 2 diabetes." (PMID 31336986, 2019).
type 2 diabetes (continued). "There is a phase 2 randomised control trial being conducted using the Janus kinase inhibitor, bacitrinib, to treat DN in Type 2 Diabetes (T2D) patients by inhibiting IL-6-mediated JAK/STAT signalling." (PMID 30871285, 2019). "Increased levels of circulating inflammatory markers (i.e., C-reactive protein [CRP] and Interleukin-6 [IL-6]) predict body mass gain in older adults and type 2 diabetes." (PMID 30979048, 2019). "IL-6 was increased in human obese individuals and in plasma of type 2 diabetic patients, because one-third of its production occurs in the white adipose tissue, mainly by macrophages and partially through adipocytes." (PMID 30823525, 2019). "Interleukin 6 (IL-6) plays an important role in wound healing and is known to be elevated in the serum of both type I and type II diabetes patients." (PMID 31073533, 2019). "Vitamin D can suppress TNF-α and IL-6 production by activated-monocytes in type 2 diabetic patients." (PMID 29684027, 2018). "There have been a small number of cross-sectional analyses performed regarding the relationship between circulating C-reactive protein, interleukin-6, fibrinogen, and type 2 diabetes." (PMID 29910771, 2018). "Children who presented within 6 h of coma onset had higher concentrations of IL-1β, IL-6, and IL-10 than those who presented more than 18 h after coma onset." (PMID 30477519, 2018). "TNF-α, IL6, MCP1 and IL1-β, were also significantly upregulated (p < 0.05) in PBMCs from patients with type 2 diabetes, implying an acquisition state of senescence-associated secretory phenotype." (PMID 30139387, 2018). "An excess of IL-6 has been measured in adipose tissue in patients with obesity and type 2 diabetes, as well as in patients with MetS." (PMID 30425746, 2018). "The circulating markers of inflammation (e.g., TNF-α and IL-6) and acute-phase reactants (e.g., CRP) are considered strong predictors of the development of type 2 diabetes and the possible associated cardiovascular complications." (PMID 29755566, 2018). "Cross-sectional studies of C-reactive protein, interleukin-6, and tumor necrosis factor-α in type 2 diabetes." (PMID 29910771, 2018). "Although only observational in nature, these studies demonstrate that in patients with type 2 diabetes and diabetic kidney disease, circulating levels of C-reactive protein, fibrinogen, interleukin-6, and tumor necrosis factor are significantly increased." (PMID 29910771, 2018). "Longitudinal studies of C-reactive protein, interleukin-6, tumor necrosis factor-α, fibrinogen, and plasminogen activator inhibitor-1 in type 2 diabetes." (PMID 29910771, 2018). "IL-6 has also been reported to be significantly high in type 2 diabetic patients with nephropathy (DN) in comparison to DM patients without DN." (PMID 28164134, 2017). "Increased IL-6 concentrations have been reported in numerous diseases such as cardiovascular diseases, Type 2 diabetes, and lymphoma, kidney, bladder, and colorectal cancers." (PMID 29410961, 2017). "Type 2 diabetes is associated with subclinical inflammation as indicated by the increase of circulating proinflammatory cytokines as such as TNF-α, IL-6, IL-1ß or IL-18." (PMID 29121068, 2017). "Overexpression of IL-6 and IL-1β in periodontally inflamed tissue has also been postulated as a mechanism by which type 2 diabetes enhances periodontal destruction." (PMID 29075409, 2017). "Many studies have demonstrated independent relationships between various inflammatory markers, such as hs-CRP and interleukin (IL)-6, and the development of type 2 diabetes." (PMID 28575103, 2017). "In summary, results obtained from this study demonstrate that RA-3 improved glucose tolerance and pancreatic beta cell ultrastructure by inhibiting inflammation through the reduction of IL-6 levels and enhanced antioxidant status of the type 2 diabetic rats." (PMID 28933769, 2017).
type 2 diabetes (continued). "Recently, Choudhary and Ahlawat analyzed serum levels of IL-6 in type 2 diabetic patients to find a correlation between IL-6 and albuminuria." (PMID 28164134, 2017). "Increased levels of serum inflammatory marker IL-6 have been found in patients with type 2 diabetes." (PMID 27965984, 2016). "Both type 1 and type 2 diabetes are associated with increased blood concentrations of several inflammatory biomarkers, including C-reactive protein (CRP), interleukin (IL)-2, IL-6 and tumour necrosis factor-alpha (TNF-α)." (PMID 27544079, 2016). "The Women’s Health Study, a prospective study about the health of middle-aged women in the USA found that elevated level of C-reactive protein (CRP) and interleukin-6 (IL-6) predict development of type 2 diabetes in women." (PMID 27581604, 2016). "Plasma levels of both TNF-α (p < 0.001) and IL-6 (p = 0.002) were significantly higher in patients with type 2 diabetes compared to control subjects." (PMID 27904654, 2016). "Another study revealed that although type 2 diabetes patients had higher serum levels of IL-6, the mRNA levels of TLR2 were lower than in healthy subjects." (PMID 28536605, 2016). "Air pollutants have been linked to type 2 diabetes (T2D), hypothesized to act through inflammatory pathways and may induce interleukin-6 gene (IL6) in the airway epithelium." (PMID 26911440, 2016). "Vinik described activation of inflammatory cytokines like IL-6 and TNFα in newly diagnosed type 2 diabetes and that the inflammatory change correlates with abnormalities in sympathovagal balance." (PMID 27992613, 2016). "For instance, pro-inflammatory cytokines including interleukin (IL)-6 and tumor necrosis factor (TNF)-α enhance insulin resistance, and are associated with increased risk of type 2 diabetes." (PMID 27904436, 2016). "In line, reduced muscle PGC-1α expression in glucose intolerant and type 2 diabetic patients significantly correlates with elevated IL-6 and TNFα." (PMID 27833743, 2016). "High doses of insulin (100 IU/ml), such as those seen in cases of type 2 diabetes, also increased IL-6 and decreased TLR2 expression." (PMID 28536605, 2016). "Plasma levels of both TNF-α and IL-6 were significantly higher (p < 0.05) in patients with type 2 diabetes compared to control subjects." (PMID 27904654, 2016). "IL–1 antagonism improves glycemia and decreases systemic inflammation including IL–6 in patients with type 2 diabetes." (PMID 26448147, 2015). "CRP and IL-6, the two most sensitive markers of inflammation have been elevated in patients with type 2 diabetes." (PMID 26153197, 2015). "The evidence that increased serum PAI-1, interleukin-6 and CRP levels are associated with the development of type 2 diabetes is growing." (PMID 26011530, 2015). "Our study demonstrates that PGRN concentrations and other inflammatory markers, such as TNF-α and IL-6, are markedly elevated in sera of type 2 diabetic patients with microangiopathy." (PMID 26106251, 2015). "With the exception of CCL-2 (p = 0.09), differences in TNF-α (p < 0.0001), hs-CRP (p < 0.05), IL-6 (p < 0.05) and adiponectin remained significant after excluding subjects with type 2 diabetes (n = 7) from the NASH cohort." (PMID 24962805, 2014). "Markers of chronic low-grade inflammation, such as tumor necrosis factor-α (TNF-α), Interleukin-6 (IL-6), and high sensitive- C-reactive protein (hs-CRP) have been shown to predict the risk of developing type 2 diabetes and cardiovascular disease." (PMID 24495354, 2014). "In the literature, it has been described that plasma IL-6 levels are associated with increased CV risk and observed in SLE patients with metabolic syndrome and in patients with type 2 diabetes." (PMID 24741576, 2014). "In a follow-up study, a synergistic elevation in circulating levels of IL-1β and IL-6 was suggested to be predictive of type 2 diabetes." (PMID 24918199, 2014).
type 2 diabetes (continued). "The antidiabetic agents, dipeptidyl peptidase IV inhibitors, were found to reduce glucose fluctuations and plasma nitrotyrosine, IL-6, and IL-18 levels (p<0.05) in type 2 diabetic patients after 3 months of treatment." (PMID 25259806, 2014). "Additional studies assessing the long-term risk factors for type 2 diabetes revealed that the levels of CRP, IL-6, IL-8, and TNF-α were higher in diabetic populations than the normal population." (PMID 25132859, 2014). "Our results first showed that the expression of inflammatory genes in duodenal tissues of obese men with type 2 diabetes is relatively low, particularly in the case of IL-6 and TNF-α." (PMID 23855973, 2013). "In type 2 diabetic patients, an acute increase in circulating insulin levels during a meal decreases plasma concentrations of IL-6 and other inflammatory cytokines." (PMID 23776669, 2013). "Low-grade inflammation has been reported in FDR of type 2 diabetics, and inflammatory markers such as hsCRP, IL6 and TNFα have been reported to induce SVI in various stress related disorders." (PMID 24265679, 2013). "Fasting plasma IL-6 levels are abnormally high in obesity and insulin resistance, and predict the development of type 2 diabetes and coronary heart disease." (PMID 23776669, 2013). "In cases of moderate upregulation of circulating levels of CRP and IL-6, such as in subclinical systemic inflammation of type 2 diabetes, this is usually accompanied by increased concentrations of soluble adhesion molecules." (PMID 23991111, 2013). "In a GK rat model of type 2 diabetes, treatment with IL-1 receptor antagonist (IL-1Ra) reduced islet mRNA expression of a number of inflammatory factors which includes: IL-1β, IL-6, TNF-α, MCP-1 and MIP-1α." (PMID 24359406, 2013). "Compared to the healthy subjects, plasma levels of the proinflammatory markers are increased (e.g., TNF-α, IL-6, and resistin), while the anti-inflammatory markers are decreased (e.g., adiponectin, leptin) in the obese subjects with type 2 diabetes." (PMID 23476101, 2013). "Further, it is reported that healthy, middle-aged women who showed high levels of inflammatory markers IL-6 and CRP had increased risk for developing type 2 diabetes over a 4-year period." (PMID 23862164, 2013). "The inflammatory markers C-reactive protein and interleukin-6 were measured repeatedly and type 2 diabetes incidence (new cases) was monitored over an 18-year follow-up (from 1991–1993 until 2007–2009)." (PMID 23843750, 2013). "Since then more studies have shown increased levels of inflammatory mediators like C-reactive protein, interleukin-6, and plasminogen activator inhibitor-1 in patients with type-2 diabetes." (PMID 22792473, 2012). "Further, increased levels of AGP1 reflect elevated levels of cytokines, such as interleukin-1 (IL-1), IL-6, and tumor necrosis factor alpha (TNF-α), which are associated with type 2 diabetes." (PMID 22536212, 2012). "Here we show that there is strong evidence of inflammation with activation of inflammatory cytokines such as IL-6 and leptin in newly diagnosed type 2 diabetes." (PMID 22110481, 2012). "On bivariate analysis, IL-6, hs-CRP, leptin and γGT were positively associated with increased risk of type 2 diabetes; IL-1β and adiponectin were inversely associated with type 2 diabetes risk." (PMID 23251619, 2012). "Systemic levels of proinflammatory cytokines, including TNF-α, IL-1β, and IL-6, are elevated in patients with both type 1 and type 2 diabetes." (PMID 23320034, 2012). "In type 2 diabetics, serum concentrations of IL-6, hs-CRP, and Hp were significantly elevated and correlated to body mass index." (PMID 23283045, 2012). "Controlling post-meal hyperglycaemia with prandial + basal insulin in patients with Type 2 diabetes attenuates meal-induced increases in high-sensitivity C-reactive protein, interleukin-6 and tumour necrosis factor α compared with basal insulin." (PMID 21517955, 2011).
type 2 diabetes (continued). "TNF-α and IL-6, incidence of known hypertension, and type-2 diabetes were significantly greater among AMI patients compared to healthy subjects." (PMID 20671994, 2010). "Several studies have suggested that type 2 diabetes is an inflammatory condition, mainly due to finding increased levels of inflammatory markers such as C-reactive protein and IL-6 in type 2 diabetics." (PMID 23675048, 2007). "Circulating levels of inflammatory cytokines such as IL-6 and TNFα are increased in type 2 diabetes." (PMID 16787541, 2006). "Notably, one CpG connected to NFATC2IP (Nuclear Factor of Activated T-cells 2 Interacting Protein) plausibly influences both IL-6 production and multiple immunometabolic conditions, including body mass index and type 2 diabetes." (PMID 41639309, 2026). "Notably, Firmicutes has also been shown to correlate positively with serum IL-6 levels in a type 2 diabetic rat model." (PMID 41596382, 2026). "The role of the cytokine IL‐6 in inflammation and Type 2 diabetes is less clear." (PMID 41559866, 2026). "The ability of BRI to predict type 2 diabetes and cardiovascular risk stems from its accuracy in estimating visceral adiposity, which produces adipokines and inflammatory cytokines such as TNF-α, IL-6, and resistin, which impair insulin signaling pathways." (PMID 40727914, 2025). "In this context, our study demonstrated that treatment of type 2 diabetic rats with FA for 28 days significantly downregulated hepatic and renal levels of key pro-inflammatory mediators – including NF-κB-p65, IL-1β, and IL-6 – compared to untreated diabetic rats." (PMID 41142063, 2025). "Anti-IL-6 strategies may be broadly applicable to a wide range of medical conditions, such as pericarditis, gout, type 2 diabetes, and others that are still under investigation." (PMID 40733185, 2025). "Research has indicated that IL-6 levels are positively correlated with disease severity in patients with type 2 diabetes, and excessive IL-6 may impair tissue repair capacity." (PMID 40677522, 2025). "Parameters indicative of chronic inflammation, such as high-sensitivity C-reactive protein, interleukin-6, and TNF-α, are significantly and independently associated with increased serum prolactin concentrations in type 2 diabetes, chronic kidney disease, and chronic heart failure." (PMID 40650124, 2025). "In type 2 diabetic mice, IL-6 and IL-10 are key mediators of inflammatory responses." (PMID 40565702, 2025). "Importantly, IL-1 antagonism reduces levels of CRP, IL-6 and leucocytosis in those with type 2 diabetes." (PMID 39496966, 2025). "IL‐6 has certain value in the course monitoring of type 2 diabetes patients with foot infection." (PMID 38577990, 2024). "Since IL-1β and IL-6 levels are increased in type 2 diabetes and are primarily released from adipose tissue and visceral fat, it can be hypothesized that these pro-inflammatory cytokines may support the accumulation of MDSCs in adipose tissue." (PMID 39518420, 2024). "However, it should be reiterated that CRP and IL-6 levels generally tend to be low in both Japanese women and men, and the prevalence of Type 2 diabetes in the MIDJA participants was only 7%." (PMID 39765763, 2024). "HP-HAW treatment suppressed Il-6 mRNA expression in the hippocampus in type 2 diabetic mice." (PMID 38997451, 2024). "Wang and colleagues conducted a meta-analysis of prospective studies to determine whether elevated levels of inflammatory markers, specifically IL-6 and CRP, are associated with an increased risk of developing type 2 diabetes." (PMID 39404426, 2024). "Clinical studies have shown that the daily consumption of beetroot juice in patients with type 2 diabetes mellitus, for a 12-week period, reduced the concentrations of inflammatory markers, including IL-6, TNF-α, and NF-κB, which are involved in the pathogenesis of complications of type 2 diabetes." (PMID 39682981, 2024).